PRPS1L1 (phosphoribosyl pyrophosphate synthetase 1 like 1)
Description:
Catalyzes the synthesis of phosphoribosylpyrophosphate (PRPP) that is essential for nucleotide synthesis.
Synonyms: PRS-III; PRPS3; PRPSL
Tractability: PROTAC: ubiquitination databases record sites on it; its protein half-life has been measured.
Gene: Protein-coding gene on chromosome 7 (18,026,770 to 18,027,846, reverse strand). Ensembl gene ENSG00000229937.
Subcellular location (Human Protein Atlas): Vesicles
Pathways (Reactome):
Metabolism: 5-Phosphoribose 1-diphosphate biosynthesis
Gene Ontology:
Molecular function: ATP binding; protein homodimerization activity; ribose phosphate diphosphokinase activity; magnesium ion binding
Biological process: 5-phosphoribose 1-diphosphate biosynthetic process; purine nucleotide biosynthetic process; male gonad development; nucleotide biosynthetic process; ribonucleoside monophosphate biosynthetic process
Cellular component: cytoplasm; ribose phosphate diphosphokinase complex
Genetic constraint (gnomAD): Loss-of-function variants: 12 observed, 16.64 expected, observed/expected ratio (o/e) 0.72, 90% interval 0.46 to 1.17. The upper end of that interval is the gene's LOEUF score, 1.17, which puts it in group 5 of 6, group 1 being the genes least tolerant of losing a copy. Missense variants: 395 observed, 401.44 expected, observed/expected ratio (o/e) 0.98, 90% interval 0.9 to 1.07. Synonymous variants: 143 observed, 139.13 expected, observed/expected ratio (o/e) 1.03, 90% interval 0.9 to 1.18.
Homologues: Orthologues: macaque PRPS1L1 (97% identical), guinea pig PRPS1L1 (93% identical), tropical clawed frog prps1 (93% identical), zebrafish prps1b (93% identical), zebrafish prps1a (92% identical), mouse Prps1l1 (92% identical), rat Prps1l1 (92% identical), Drosophila melanogaster Prps (86% identical), Caenorhabditis elegans R151.2 (80% identical), dog PRPS1L1 (61% identical). Paralogues in human: PRPS1 (94% identical), PRPS2 (91% identical), PRPSAP2 (48% identical), PRPSAP1 (48% identical).
Diseases named in the same sentence as PRPS1L1 in open-access papers:
PRPS1L1 is named in the same sentence as 4 diseases in open-access papers, as found by Europe PMC text mining. Sharing a sentence is not in itself a finding about the gene and the disease. The quoted sentences say what the papers report.
Ataxia (1 paper, 2019). Ataxia refers to impaired coordination of voluntary muscle movement. "PRPPS (Prps1, Prps1l1, Prps2) was previously reported to be affected by amino acid depletion, while mutations in Prps1 have been associated with hyperuricemia, hyperuricosuria, hypotonia, and ataxia and gain-of-function mutation results in PRS-1 superactivity." (PMID 31285465, 2019).
COVID-19 (1 paper, 2023). A disease caused by infection with severe acute respiratory syndrome coronavirus 2. "In the plasma of the COVID-19 patients studied, a large group of modified MDA proteins are kinases (MAP kinase-activated protein kinase 2 (MAPKAPK2, P49137), ribose-phosphate pyrophosphokinase 3 (PRPS1L1, P21108), and cAMP-dependent protein kinase (PKA, P22612))." (PMID 37762413, 2023).
PRPS1L1 also shares sentences with these, for which no sentence is quoted: hyperuricemia (1 paper); infection (1).